B2M (beta-2-microglobulin)
Diseases named in the same sentence as B2M in open-access papers (continued):
Sharing a sentence is not in itself a finding about the gene and the disease.
chronic kidney disease (17 papers, 2012 to 2025). Impairment of the renal function secondary to chronic kidney damage persisting for three or more months. "High levels of B2M are linked to both mortality and morbidity in end-stage renal disease (ESRD), including vascular calcification." (PMID 36648873, 2022). "Increase of B2M has been associated with death in patients with chronic kidney disease." (PMID 34139154, 2021). "End-stage chronic kidney disease (CKD) leads to accumulation of B2M in peripheral tissues, which is an established cause of systemic amyloidosis in patients undergoing dialysis." (PMID 24757603, 2012). "We describe a systematic protein design effort aimed at adding the ability to selectively remove specific, undesired waste proteins such as B2M from the plasma of chronic renal failure patients." (PMID 37509158, 2023). "In this paper, we revisit the role of beta-2 microglobulin (β2M) as a biomarker in patients with chronic kidney disease and end-stage renal disease." (PMID 28664159, 2017). "Both urinary beta-2-microglobulin, a biomarker of chronic kidney disease, and N-acetyl-beta-D-glucosaminidase, a biomarker of renal tubular impairment were significantly elevated in the HE compared with LE (P < 0.0001 and P = 0.0036, respectively)." (PMID 29492308, 2017). "This study defines the relationship between salivary beta-2 microglobulin(β2-M) and intensity of uremia in male patients diagnosed with chronic renal failure(CRF)." (PMID 23577307, 2013). "Higher B2M serum concentrations are associated with higher mortality in the general population, non-dialyzed chronic kidney disease patients, and patients receiving hemodialysis (HD)." (PMID 39335603, 2024). "Higher serum β2-microglobulin (B2M) concentrations are associated with higher mortality in the general population, non-dialyzed chronic kidney disease patients and patients receiving hemodialysis (HD)." (PMID 35421178, 2022). "However, B2M plasma levels are commonly elevated in patients with chronic kidney disease (CKD) as a result of decreased glomerular filtration rate (GFR) and the CLL-IPI risk model was not adjusted for compromised renal function." (PMID 39594701, 2024). "Owing to the high morbidity of cardiovascular diseases (CVD) in patients with chronic kidney disease (CKD), renal biomarkers such as beta-2-microglobulin (B2M), cystatin C and lipocalin-2 (LCN-2) have attracted increasing attention." (PMID 37155257, 2023). "In addition, the positive association of B2M and CVD, CHD or stroke appeared slightly stronger in individuals without chronic kidney disease than those with chronic kidney disease in one study." (PMID 33581388, 2021).
colon carcinoma (17 papers, 2008 to 2025). "The FOGT-4 cohort was retrospectively analysed for MSI, and B2M mutation status as potential prognostic or predictive markers in colon cancer." (PMID 22353804, 2012). "In the subgroup of MSI-H colon cancer patients, B2M mutation status was determined to evaluate potential associations of B2M mutations with prognosis in MSI-H colon cancer." (PMID 22353804, 2012). "B2M mutation analysis should therefore be included as a potential prognostic marker in future colon cancer therapy trials." (PMID 22353804, 2012). "This study aimed at the evaluation of MSI and B2M mutation status as potential prognostic or predictive markers in patients with colon cancer, eligible for adjuvant chemotherapy enrolled in the controlled prospective FOGT-4 chemotherapy trial." (PMID 22353804, 2012). "Subclassification of MSI-H colon cancer patients according to B2M mutation status revealed that B2M wild-type MSI-H colon cancer patients were comparable to MSS colon cancer patients with regard to TTR." (PMID 22353804, 2012). "For example, in HCT-15 colon cancer cells, both B2M alleles are mutated, one by an 11 base-pair deletion and the other by a point mutation, resulting in the loss of HLA class 1 surface antigens." (PMID 18506145, 2008). "Taken together, these results show that ICB treatment of MMR-d colon cancer increases the presence of activated, cytotoxic and proliferating γδ T cells at the tumour site, especially when these cancers are B2M-deficient, highlighting γδ T cells as effectors of ICB treatment within this context." (PMID 36631610, 2023). "It is enriched in different types of cancer, including breast, bladder and MSS colon carcinomas and it might be the initial event toward complete loss of the B2M gene." (PMID 34680201, 2021). "Furthermore, mutation of the B2M gene in MSI-H colon cancers is an independent positive prognostic factor." (PMID 29121062, 2017). "The mechanism contributing to a decreased metastatic potential of B2M-mutant, HLA class I-deficient colon cancer cells may involve NK cell-mediated tumour cell lysis." (PMID 22353804, 2012). "Truncating B2M mutations were identified in 10 (29.4%) out of 34 MSI-H colon cancers." (PMID 22353804, 2012). "This is suggestive of the hypothesis that the improved prognosis previously reported for MSI-H colon cancer patients is related to the frequent occurrence of B2M mutations in this tumour type." (PMID 22353804, 2012). "Mutations of the B2M gene have been reported as a frequent event in MSI-H colon cancer." (PMID 22353804, 2012). "Thus, subgroup analysis was performed to determine a potential prognostic role of B2M mutation status within the MSI-H colon cancer group." (PMID 22353804, 2012). "In addition to inactivation by K-ras mutations in colon cancer, B2M gene expression can also be impaired by mutations in the coding and non-coding (promoter) regions." (PMID 18506145, 2008). "Moreover, B2M mutations may contribute to the favourable outcome of MSI-H colon cancer patients and should therefore be evaluated as a potential prognostic marker in future clinical trials." (PMID 22353804, 2012). "However, Natasja and his colleagues isolated γδT cells from 5 mismatch repair-deficient (MMR-d) colon cancer tissue for scRNA-seq, revealing that PD-1, activation, proliferation and killer genes expressed by γδ1 and γδ3 T cells were significantly upregulated in B2M-deficient tumors." (PMID 40191187, 2025). "Intriguingly, high B2M expression showed significantly better prognosis than low B2M expression in colon cancer (p = 0.0021) similarly with CD8A, IFNG and TLR4." (PMID 38557819, 2024). "Several of these antigen processing and presentation genes, with B2M being the most significant, were higher on average in three normal colon samples compared to four colon cancer samples." (PMID 28622390, 2017). "Further studies on the mechanisms underlying B2M inactivation and metastasis formation in MSI-H colon cancer will be warranted." (PMID 22353804, 2012).
colon carcinoma (continued). "We here analysed the prognostic significance of MSI and mutations of the Beta2-Microglobulin (B2M) gene, which occur in about 30% of MSI-H colon cancer, in the cohort of the prospective FOGT-4 (Forschungsruppe Onkologie Gastrointestinale Tumoren, FOGT) trial." (PMID 22353804, 2012). "B2m was deleted in ICB-responsive MC38 murine colon cancer cells." (PMID 38427670, 2024). "B2m deletion was also examined in the MC38 murine colon cancer model." (PMID 38427670, 2024). "By comparing paired tumour samples from patients with MMR-d colon cancer that were obtained before and after dual PD-1 and CTLA-4 blockade, we found that immune checkpoint blockade substantially increased the frequency of γδ T cells in B2M-deficient cancers." (PMID 36631610, 2023). "B2M mutant colon cancers formed large primary tumors but rarely metastasized." (PMID 29121062, 2017). "This suggests that B2M mutations, beyond their association with M0 stage at the time point of colon cancer diagnosis, may predict a favourable outcome in MSI-H colon cancer patients." (PMID 22353804, 2012). "B2M, which encodes the small chain of the MHC I molecule crucial for MHC I assembly, was expressed at lower levels in colon cancer cell lines relative to normal colon However, 3/8 colon cancer cell lines significantly upregulated B2M after treatment with low doses of 5-AC." (PMID 28622390, 2017). "Alternatively, B2M mutations may directly influence the oncogenic potential of MSI-H colon cancer cells in an HLA-independent manner, as B2M has recently been demonstrated to enhance epithelial-to-mesenchymal transition and promote bone metastasis in several human cancer types." (PMID 22353804, 2012). "The absence of liver metastases in patients with B2M-mutant MSI-H colon cancer led us to hypothesise that B2M mutations might interfere with metastasis formation and thus have a potentially favourable prognostic effect in MSI-H colon cancer patients." (PMID 22353804, 2012). "In vitro, PD-1+ γδ T cells that were isolated from MMR-d colon cancers exhibited enhanced reactivity to human leukocyte antigen (HLA)-class-I-negative MMR-d colon cancer cell lines and B2M-knockout patient-derived tumour organoids compared with antigen-presentation-proficient cells." (PMID 36631610, 2023). "Despite the known biological properties of B2M, this gene has been inadvertently used as an internal reference control in studies involving IFN signalling, as well as real-time PCR studies of colon cancer prognosis." (PMID 18506145, 2008).
diabetes (17 papers, 2013 to 2024). "Glycation of B2M may contribute to the risk of diabetes associated complications." (PMID 28761062, 2017). "Like BTP, the role of B2M in diabetes has been extensively studied; a recent meta-analysis of 8 cohort studies has shown that B2M levels are associated with increased risk of DKD." (PMID 39055699, 2024). "Its role as an inflammation marker is corroborated by studies reporting positive associations of B2M with CVD, diabetes, and mortality from those diseases and all causes." (PMID 35647083, 2022). "The increased serum concentration of beta-2 microglobulin (B2M) is used as a clinical marker for diabetes mellitus, and high-mobility group protein B2 (HMGB2) is used as a diagnostic marker for both obese and diabetic patients." (PMID 34561612, 2021). "Beta-2-microglobulin (B2M) has been extensively studied in relation to diabetes, kidney disease, and cardiac events." (PMID 26074879, 2015). "These were LVEF (0.27), the number of implanted stents (0.14), age (0.13), diabetes (0.10), the number of vessels with coronary artery disease (0.09), vascular disease (0.08), brain natriuretic peptide (0.05), glucose (0.05), beta 2 microglobulin (0.04), and abnormal Q wave (0.02)." (PMID 38170581, 2024). "Urine beta-2 microglobulin levels, an exploratory biomarker that was measured as a potential early indicator of renal toxicity, were within the normal range at both baseline and after treatment for all subjects except for two subjects with diabetes." (PMID 23668634, 2013). "Specifically, five genes—ATF4, ATP1A1, B2M, CYBA, and PRNP—emerged with the highest inference scores in the context of T2D and Diabetes Mellitus, suggesting that these genes play critical roles in the molecular mechanisms underlying these conditions." (PMID 39926598, 2024). "B2M was also highly excreted in the proteinuria group without diabetes (Ctr vs. NP p < 0.05)." (PMID 32121033, 2020).
glioma (17 papers, 2019 to 2025). A benign or malignant brain and spinal cord tumor that arises from glial cells (astrocytes, oligodendrocytes, ependymal cells). "Kaplan-Meier analysis, alongside uni- and multivariate Cox regression, assessed the association between B2M levels, systemic inflammatory markers, and glioma patient prognosis." (PMID 38844902, 2024). "Based on the analyses of pan-cancer, B2M expression was highly associated with human primary glioblastoma cell line—U87 cell lineage and gliomas samples, including LGG and GBM." (PMID 33658560, 2021). "Somatic mutations of gliomas with high B2M expression are associated with PTEN deletion and EGFR amplification." (PMID 33658560, 2021). "Here, we explored the potential of β2-microglobulin (B2M) to serve as a hopeful candidate for immunotherapy or diagnostic biomarker in gliomas." (PMID 33658560, 2021). "Isocitrate dehydrogenase (IDH) mutations accounted for 82% in gliomas with low B2M expression." (PMID 33658560, 2021). "Taken together, B2M was associated with the malignancy of gliomas." (PMID 33658560, 2021). "Moreover, gliomas with CN loss showed low expression of B2M." (PMID 33658560, 2021). "Meta-analysis further established B2M as an independent prognostic marker in glioma, with moderate sensitivity in predicting the mesenchymal molecular subtype." (PMID 40842996, 2025). "B2M is overexpressed in gliomas, correlates with tumor grade, immune infiltration, and mesenchymal subtype; lower expression predicts longer survival, highlighting B2M as a prognostic biomarker and potential therapeutic target." (PMID 41179304, 2025). "Consistent with our results, recent research has illuminated the pivotal role of B2M in maintaining the properties of glioma stem cells (GSCs)." (PMID 38743119, 2024). "Recent studies by our research team and others have found that B2M mRNA and protein levels were significantly elevated in glioma when compared to normal brain tissue." (PMID 38743119, 2024). "Concerning treatment, the findings of B2M in Alzheimer's disease, stroke, ageing, and gliomas highlighted the therapeutic potential of B2M in CNS diseases." (PMID 38743119, 2024). "Multivariate Cox analysis determined the relationship between B2M levels (hazard ratio = 1.92, 95% confidence interval: 1.05-3.50, P = 0.034) and the overall survival of glioma patients." (PMID 38844902, 2024). "The expression levels of B2M exhibited a positive correlation with the malignancy grade of glioma, and higher B2M expression was related to a poorer prognosis in glioma patients." (PMID 38743119, 2024). "Reportedly, highly expressed B2M can predict the poor prognosis of glioma patients and mediate immune cell infiltration via chemokines." (PMID 37759870, 2023). "Since the expression pattern of B2M in glioma specimens is not clear, we used large-scale bioinformatics analysis to study the distribution of B2M in gliomas." (PMID 33658560, 2021). "We found that the cytokine signaling pathway, NF‐kappa B signaling pathway, and Toll‐like receptor signaling pathway were involved in B2M‐related pathways in glioma samples." (PMID 33960680, 2021). "Results showed that the areas under the curves(AUCs) varied from 63.24% to 70.31% among the three databases, indicating that B2M possessed a moderate sensitivity and specificity for predicting the mesenchymal molecular subtype of gliomas." (PMID 33960680, 2021). "The results of GO enrichment and KEGG pathway analysis revealed that B2M regulated immune infiltration via chemokines in gliomas." (PMID 33960680, 2021). "According to the WHO classification of gliomas, B2M had the highest expression level in GBM samples (Grade IV) in TCGA and CGGA." (PMID 33658560, 2021). "To determine which leukocyte cell type was associated with B2M‐mediated immune responses, we divided samples into high and low B2M expression groups and then analyzed immune infiltration in gliomas based on the TIMER dataset." (PMID 33960680, 2021).
glioma (continued). "The top‐10 GO terms in biological processes suggested that B2M was mainly involved in regulating immune response in gliomas." (PMID 33960680, 2021). "B2M was more upregulated in CL and ME subtypes in pan-gliomas and LGGs compared to PN and NE subtypes." (PMID 33658560, 2021). "In the present study, we first measured B2M mRNA and protein levels in glioma tissues and normal brain tissues from public datasets." (PMID 33960680, 2021). "After determining the roles of B2M in glioma immune infiltration in our present study, we next performed KEGG pathway analysis to explore the related mechanisms." (PMID 33960680, 2021). "Tumor with high B2M expression had increased MHC-I-based antigen presentation and associated CD8 cytolytic responses, which gliomas were likely to adopt immune evasive mechanisms through expression of immune checkpoint molecules." (PMID 33658560, 2021). "Then, we explored the B2M expression in gliomas with respect to World Health Organization (WHO) grade, IDH1 status, and different molecular subtypes." (PMID 33960680, 2021). "Surprisingly, the AUC value of B2M expression in predicting CL and ME subtypes were 91.4% and 90.7% in pan-gliomas and LGGs, respectively, indicating that B2M effectively predicted the more aggressive subtypes." (PMID 33658560, 2021). "Forest plot shows that high B2M expression corresponded to a poor survival time compared to that of low B2M expression in glioma patients from three databases." (PMID 33960680, 2021). "Compared with that in the proneural molecular subtype, B2M expression was higher in the mesenchymal molecular subtype among the three glioma databases." (PMID 33960680, 2021). "GO and KEGG analysis were performed to explore biological roles of B2M in the occurrence and development of human gliomas." (PMID 33658560, 2021). "The high correlation between MHC-I and B2M expression further confirmed the B2M-induced MHC-I-based antigen presentation forced gliomas to express more immune checkpoint molecules to escape immune surveillance." (PMID 33658560, 2021). "We conclude that B2M levels are critical for the survival times of glioma patients, at least in part due to mediating high immune infiltration." (PMID 33960680, 2021). "Glioma patients with high levels of B2M expression had a poor overall survival compared to that of glioma patients with comparatively lower levels of B2M expression." (PMID 33960680, 2021). "Further, we explored the prognostic value of B2M by assessing its ability in distinguishing glioma patients." (PMID 33658560, 2021). "Subsequently, we investigated the prognostic value of B2M in human gliomas using Kaplan–Meier analysis." (PMID 33658560, 2021). "The results of ROC analysis indicated that B2M possessed a moderate sensitivity and specificity for predicting the mesenchymal molecular subtype of gliomas." (PMID 33960680, 2021). "GO(Gene‐ontology) enrichment analysis, co‐expression analysis, KEGG(Kyoto Encyclopedia of Genes and Genomes) pathway analysis, and immune infiltration analysis were performed to explore roles and related mechanisms of B2M in glioma." (PMID 33960680, 2021). "To further explore the expression patterns of B2M in gliomas, we evaluated the distribution of B2M in different molecular subtypes." (PMID 33960680, 2021). "Our previous study showed that serum levels of beta‐2 microglobulin (B2M) in lower‐grade glioma patients were lower than those in glioblastoma patients." (PMID 33960680, 2021). "To validate this result, we performed receiver operating characteristic curve (ROC) analysis for B2M expression in the mesenchymal molecular subtype of gliomas." (PMID 33960680, 2021). "To validate these findings, we detected B2M protein levels in 103 glioma tissues by immunofluorescence assay." (PMID 33960680, 2021). "To sum up, based on our bioinformatics analysis, we confirmed that B2M, as a molecular target, played a potential role in the anti-cancer treatment of glioma." (PMID 33658560, 2021).